STAT3 (signal transducer and activator of transcription 3)
Diseases named in the same sentence as STAT3 in open-access papers (continued):
Sharing a sentence is not in itself a finding about the gene and the disease.
pancreatic cancer (continued). "The epidermal growth factor receptor (EGFR), which activates STAT3, is reportedly overexpressed in human pancreatic cancer cells." (PMID 30400136, 2018). "The IL-6/STAT3 pathway in PSCs, which recruits MDSCs to the pancreatic cancer microenvironment, also displays the function of promoting EMT by activating nuclear factor erythroid 2 (Nrf2)." (PMID 30060755, 2018). "As is the case with many other malignancies, constitutively activated signal transducers and activators of transcription factor 3 (STAT3) play a key role in pancreatic cancer." (PMID 30400136, 2018). "In pancreatic cancer stem cells, STAT3 is activated, but STAT3 inhibition decreases both radioresistance and stem cell numbers in pancreatic cancer." (PMID 29439394, 2018). "In pancreatic cancer, STAT3 was observed during all stages of pancreatic oncogenesis, and inhibition or loss of STAT3 reduced oncogenic KRAS-induced ADM and PanIN formation." (PMID 28738823, 2017). "STAT3 is a key regulator of pancreatic cancer development and progression and recent evidence indicates that these effects are mediated by STAT3-induced stroma remodeling and increased ECM stiffness." (PMID 28886117, 2017). "Our current study provides evidence that extracellular nucleosomes promote IL-6 secretion by myeloid cells, which in turn sustains STAT3 and K-Ras signaling in pancreatic cancer cells." (PMID 28374746, 2017). "Previous studies have shown that p38 activation enhances PP2Acα up-regulation resulting in MMP mRNA decay and the inhibition of JAK/STAT3 that are both important for pancreatic cancer progression." (PMID 28418923, 2017). "Suppression of GPRC5a results in decreased cell growth, proliferation and migration in pancreatic cancer cell lines via a STAT3 modulated pathway, independent from ERK activation." (PMID 28114355, 2017). "They suggest further study on STAT3 inhibition using the same model as an important tool to uncover alternative pathways to be explored in pancreatic cancer treatment." (PMID 28970834, 2017). "Pancreatic cancer-derived exosomes also induced Stat3 activation and myeloid infiltration (over 12 d of treatment)." (PMID 28969005, 2017). "We and others have shown that leptin promotes the proliferation and an invasive potential of pancreatic cancer cells through STAT3 mediated signaling." (PMID 29156726, 2017). "EGFR or STAT3 feedback activation in response to MEK inhibitors was also shown to limit efficacy in pancreatic cancer cells." (PMID 29262554, 2017). "Recent studies have demonstrated that the constitutive activation of STAT3 and the subsequent promotion of tumor cell growth, invasion, and metastasis in pancreatic cancer patients results in high mortality." (PMID 28418923, 2017). "The oncogenic STAT3 protein is constitutively activated in many human cancers, including pancreatic cancer." (PMID 28418923, 2017). "Combination therapy with MEK and STAT3/EGFR inhibitors has been demonstrated to exert significant anti-pancreatic cancer efficacy." (PMID 29262554, 2017). "Further, MMP-7 (matrilysin) triggers the invasive and metastatic capacity of pancreatic ductal adenocarcinoma cells via a STAT3-dependent mechanism that is also demonstrated in the prostate, breast and pancreatic cancer cell lines." (PMID 28418923, 2017). "Activation of STAT3 has been shown to occur frequently in cell lines and in human pancreatic cancers, which correlates with progression of disease." (PMID 29156726, 2017). "In pancreatic cancer, down-regulation of STAT3 expression suppressed the growth and invasiveness of cancer cells, both in vitro and in vivo." (PMID 28418923, 2017). "In fact, the STAT3 signaling pathway is now considered to be a crucial molecular target when it comes to pancreatic cancer." (PMID 28970834, 2017). "DON treatment appeared to effectively increase ROS in GEM-R pancreatic cancer cells, in the context of inhibiting Akt, STAT3, and MAPK dependent pathways." (PMID 28801576, 2017).
pancreatic cancer (continued). "Nevertheless, genetic knockdown or pharmacological inhibition of ILK caused depleted MUC1-C expression in IL-6-treated pancreatic cancer cells, indicating that ILK is required to sustain STAT3-induced MUC1 upregulation by maintaining its stability." (PMID 28692035, 2017). "negative HIC1 expression predicted poor dignosis; inhibited the invasion and metastasis of pancreatic cancer cells both in vitro and in vivo; repressed the expression of STAT3 target genes, including c-Myc, VEGF, CyclinD1, MMP2 and MMP9." (PMID 29254283, 2017). "Here we investigated the potential of STAT3 inhibition in sensitizing pancreatic cancer to chemo/radio-therapy." (PMID 26887043, 2016). "Since Stat3 activation plays an important role in pancreatic cancer progression, we further examined the ability of LTP-1 to inhibit Stat3 phosphorylation." (PMID 27278358, 2016). "Herein we demonstrated that OV exerted the anticancer potential in pancreatic cancer cell lines through inhibiting cell proliferation and inducing apoptosis and partly took a route via NF-κB and STAT3 pathway." (PMID 27242913, 2016). "We recently reported that HAb18G/CD147 is an upstream activator of STAT3 signaling in pancreatic cancer; the STAT3 pathway is a critical pathway that is activated in gemcitabine-resistant cells." (PMID 27556697, 2016). "It is found that STAT3 forms a positive loop with two inflammatory cytokines IL-6 and IL-11 in pancreatic cancer: STAT3 directly affects the expression of IL-6 and IL-11, both of which are STAT3 activating cytokines." (PMID 26887043, 2016). "Taken together, Lip-FLLL32 efficiently and safely delayed in vivo pancreatic tumor growth in a STAT3-dependent manner." (PMID 26887043, 2016). "Although there is abundant evidence supporting the role of Stat3 in pancreatic cancer to justify the discovery of novel Stat3 therapeutics, only few show promising activity in terms of Stat3 inhibition in vitro and an associated antitumor effect." (PMID 27278358, 2016). "Liposomal delivery of a STAT3 inhibitor FLLL32 (Lip-FLLL32) inhibited STAT3 phosphorylation and STAT3 target genes in pancreatic cancer cells and tumors." (PMID 26887043, 2016). "Reg3α, a small secretory protein belonging to the calcium-dependent lectin superfamily, also contribute to M2-polarized phenotype through the activation of STAT3 pathway in an orthotopic mouse model of pancreatic cancer." (PMID 27191744, 2016). "In pancreatic cancer cells, PPARγ activation by PPARγ agonists suppressed STAT3 expression through transcriptional repression to inhibit cell growth." (PMID 27483249, 2016). "Our findings showed that RES significantly inhibited the phosphorylation of STAT3 and NFκB in pancreatic cancer cells." (PMID 27539371, 2016). "TRES, similarly to RES, inhibited the phosphorylation of STAT3 and NFκB, down-regulated Mcl-1, and up-regulated Bim and Puma in pancreatic cancer cells." (PMID 27539371, 2016). "Within murine endothelial cells, STAT3 is activated by pancreatic cancer cell-derived pro-inflammatory and pro-angiogenic factors, leading to the up-regulation of HDAC9 which then enhances murine endothelial cell proliferation." (PMID 26586478, 2016). "IL6 induced STAT3 phosphorylation in both MiaPaCa2 and Panc01 pancreatic cancer cell lines, but only in one of the two healthy donor-derived monocytes." (PMID 27687804, 2016). "We have shown that blocking upstream activators of STAT3 inhibits pancreatic tumor growth and post-radiation recurrence partly by eradicating CSCs." (PMID 26887043, 2016). "Leptin signaling via JAK2/STAT3 enhances cell invasion and promotes the metastasis of human pancreatic cancer." (PMID 27036040, 2016). "We observed that the interaction between STAT3 and NFκB in pancreatic cancer cells were interrupted by the treatment with 50 μM TRES or RES for 72 h in PANC-1 cells." (PMID 27539371, 2016).
pancreatic cancer (continued). "We comparatively evaluated their effects on cell proliferation, apoptosis and the molecular changes in STAT3, NFκB and apoptotic signaling pathways in pancreatic cancer cells." (PMID 27539371, 2016). "Recently, others and we reported that CD147 is overexpressed in highly aggressive pancreatic cancer and acts as a novel upstream activator in STAT3-mediated pancreatic tumor development." (PMID 27556697, 2016). "The dysregulation of these genes due to the persistent activation of both NFκB and STAT3 in tumors and tumor microenvironment is crucial for the progression of pancreatic tumor." (PMID 27539371, 2016). "Our data provides important pre-clinical information and rationale for targeting IL-6/STAT3 signaling in pancreatic cancer." (PMID 27602757, 2016). "MiR-20a can down-regulate STAT3 protein expression and inhibit cell proliferation and invasion in pancreatic carcinoma." (PMID 27708666, 2016). "Taken together, our results suggest that capsaicin-induced apoptosis in pancreatic cancer cells was associated with inhibition of β-catenin signaling due to the dissociation of β-catenin/TCF-1 complex and the process was orchestrated by STAT-3." (PMID 25869100, 2015). "In order to understand the molecular basis of silibinin-mediated c-MYC expression regulation and metabolic reprogramming of pancreatic cancer cells, we investigated the effect of silibinin treatment on STAT3 activation, which enhances c-MYC expression." (PMID 26510913, 2015). "STAT3 pathway, inhibited by Capsaicin treatment, induces cell death in cancer cells resistant to conventional chemotherapies, as for example MM and pancreatic cancer." (PMID 26338963, 2015). "Our results also demonstrate that treatment of pancreatic cancer cells with silibinin leads to reduced phosphorylation of STAT3." (PMID 26510913, 2015). "STAT3 is a key player in inflammation-related tumorigenesis, including pancreatic cancer, by promoting tumor cell proliferation and survival." (PMID 26056043, 2015). "IL-6 functions in pancreatic tumor progression by activating the signal transducer and activator of transcription 3 (STAT3), as well as NF-κB in macrophages." (PMID 26404380, 2015). "In turn, IL-6 regulates signal transducer and activator of transcription 3 (STAT3), a transcription factor which is necessary for the development and progression of pancreatic cancer." (PMID 26633513, 2015). "Overall our results demonstrated that capsaicin mediated inhibition of β-catenin/TCF-1 signaling results in apoptosis which was orchestrated by STAT-3 in pancreatic cancer cells in vitro and in vivo." (PMID 25869100, 2015). "Our preliminary results have shown that the MEK inhibition in K-Ras mutant pancreatic cancer cells and colon cancer cells unexpectedly induced STAT3 phosphorylation/activation." (PMID 25961376, 2015). "Our results are in agreement with the studies, which suggest that STAT-3 regulates β-catenin/TCF-1 signaling to promote pancreatic tumor progression." (PMID 25869100, 2015). "Given that persistent low-grade inflammation is an important factor for the development of pancreatic cancer, it is worth noting that two major inflammatory mediators, STAT3 and NFкB, also can be suppressed by metformin and aspirin." (PMID 26056043, 2015). "Our results show that STAT-3 inhibitor increased capsaicin mediated suppression of β-catenin/TCF-1 signaling, suggesting a regulatory role of STAT-3 in β-catenin/TCF-1 signaling in pancreatic cancer cells." (PMID 25869100, 2015). "According to another study, let-7 downregulates STAT3 phosphorylation in pancreatic cancer cells by increasing SOCS3 expression." (PMID 25856466, 2015). "Whereas many studies have indicated that STAT-3 regulates cyclin D1, some studies suggest that this transcription factor also alters the expression of other cyclins such as cyclin E in pancreatic cancer and cyclin A in our findings." (PMID 26418031, 2015).
pancreatic cancer (continued). "Stat3 inhibition combined with targeted therapy has been proved to significantly suppress cancer cell growth in pancreatic cancers." (PMID 25057499, 2014). "Recently we reported that Nexrutine® (Nx), a Phellodendron amurense bark extract exhibits excellent anticancer activity in human pancreatic cancer cells through selective modulation of inflammatory signaling via STAT3/NFκB/Cox-2." (PMID 24796733, 2014). "The role of STAT3 in anoikis resistance has also been confirmed in pancreatic cancer (unpublished data)." (PMID 25216522, 2014). "Overall, our findings reveal an important role for STAT3/LC3/ROS in Nx-mediated anti-pancreatic cancer effects." (PMID 24796733, 2014). "Overexpression and activation of STAT3 occurs in many human cancers including pancreatic cancer and leads to tumor cell growth, invasion, and metastasis." (PMID 24796733, 2014). "Recent studies from our laboratory have shown that Nexrutine® (Nx), a bark extract from Phellodendron amurense exhibits excellent anticancer activity in human pancreatic cancer cells through inhibition of inflammatory signaling via STAT3/NFκB/Cox-2." (PMID 24796733, 2014). "It inhibited proliferation and invasion of pancreatic cancer cells by directly modulating signal transducer and activator of transcription 3 (STAT3)." (PMID 25387077, 2014). "In pre-clinical studies, miR-181b has been shown to promote cellular proliferation and reduce apoptosis in cervical cancer cells, mediate tumorigenesis through STAT3, and induce gemcitabine resistance in pancreatic cancer cells." (PMID 24732316, 2014). "The NF-κB/STAT3 inhibitor RTA 402 is currently undergoing phase I/II clinical testing for pancreatic cancer and a phase I trial in patients with solid tumors and lymphoid malignancies has already been completed." (PMID 25268165, 2014). "Recently, it was reported that silencing receptor for advanced glycation end products (RAGE) or Atg5 using shRNA significantly inhibited IL-6 induced autophagy and mitochondrial STAT3 activation in pancreatic cancer cells." (PMID 24796733, 2014). "Targeting mitochondrial STAT3, e.g., by inhibiting its mitochondrial import, has shown promise in the treatment of pancreatic cancer in animal models." (PMID 25268165, 2014). "In 42 different receptor tyrosine kinase (RTKs) array, Crizotinib also strongly inhibited the expression of activated ALK in pancreatic cancer cells, modulating its downstream mediators such as STAT3, AKT, and ERK." (PMID 25193856, 2014). "In one study, transfection of STAT3-DN in pancreatic cancer cells suppressed tumor growth and liver metastasis in nude mice, whereas transfection of STAT3C enhanced tumor growth and liver metastasis." (PMID 24995504, 2014). "Curcumin inhibits STAT3 activation in various cell lines including multiple myeloma, pancreatic cancer cell lines, Hodgkin's lymphoma, head and neck squamous cell carcinoma, primary effusion lymphoma, human chronic myelogenous leukaemia and ovarian cancer." (PMID 24199193, 2013). "The qRT-PCR and western blot results showed that the overexpression of miR-130b downregulated the expression of STAT3 in pancreatic cancer cells by both interfering with and degrading mRNA, whereas the anti-miR-130b upregulated the STAT3 expression." (PMID 24040078, 2013). "Consistent with an oncogenic role in pancreatic cancer, we show that inhibition of STAT3 reduced pancreatic cancer cell invasion and soft agar colony formation, similar to the effect of PKCζ inhibition." (PMID 24015205, 2013). "Our data also identify STAT3 as an important mediator of PKCζ in the transformed growth and invasion of pancreatic cancer cells." (PMID 24015205, 2013). "Signal transducer and activator of transcription 3 (STAT3) is often constitutively active in pancreatic cancer, and plays an important role in pancreatic cancer cell survival and metastasis." (PMID 24015205, 2013).
pancreatic cancer (continued). "This is the first report to document a cancer promotive role for PKCζ in pancreatic cancer, and to implicate PKCζ in the positive regulation of constitutive STAT3 signaling in cancer cells." (PMID 24015205, 2013). "A significant inverse correlation was observed between STAT3 and miR-130b expressions in pancreatic cancer tissues (Spearman’s correlation, r = −0.4903; P<0.01) and adjacent noncancerous tissues (r = −0.4026; P<0.001)." (PMID 24040078, 2013). "This study also implied that miR-130b played an important role in the regulation of pancreatic cancer malignant behavior including cell proliferation and invasion by directly targeting STAT3." (PMID 24040078, 2013). "A significant reduction in STAT3 activation, detected as phosphorylation of STAT3 on Tyr705, was observed in pancreatic cancer cells expressing PKCζ RNAi." (PMID 24015205, 2013). "Taken together, these data demonstrate that inhibition of PKCζ expression reduces STAT3 activity in pancreatic cancer cells, and that PKCζ expression and STAT3 activity positively regulate pancreatic cancer cell transformed growth and invasion." (PMID 24015205, 2013). "Our results indicate that P-V is a promising candidate drug against pancreatic cancer and establish mitochondrial STAT3 as its key molecular target." (PMID 23650499, 2013). "We provide strong evidence that PKCζ RNAi-mediated reduction in invasion and soft agar colony formation is due, at least in part, to down-regulation of constitutive STAT3 activity in pancreatic cancer cells." (PMID 24015205, 2013). "Our future studies will investigate the mechanism by which PKCζ promotes STAT3 activation in pancreatic cancer cells." (PMID 24015205, 2013). "We conclude that PKCζ is required for pancreatic cancer cell transformed growth and invasion in vitro and tumorigenesis in vivo, and that STAT3 is an important downstream mediator of the pro-carcinogenic effects of PKCζ in pancreatic cancer cells." (PMID 24015205, 2013). "In pancreatic cancer, activation of STAT3 promoted tumor cell growth and invasion, which led to poor patient survival." (PMID 24040078, 2013). "This association of zinc transporters with STAT3 is not unprecedented as ZIP14 is regulated by IL-6 (interleukin 6) and STAT3 signalling and ZIP4 activates STAT3 transcription in pancreatic cancer." (PMID 23919497, 2013). "While inhibition of Src or EGFR signaling pathways temporarily reduces constitutive STAT3 in pancreatic cancer cell lines, reactivation of STAT3 occurs rapidly." (PMID 24015205, 2013). "XZH-5 was found to inhibit STAT3 phosphorylation (Tyr705) and induce apoptosis in human breast and pancreatic cancer cell lines expressing elevated levels of phosphorylated STAT3." (PMID 23056374, 2012). "Inhibition of STAT3 by shRNA in pancreatic cancer cells enhances the inhibitory effects of EGCG on cell migration and motility." (PMID 22348037, 2012). "An exciting finding in this study is the dramatic synergy seen between APE1 and STAT3 blockade in patient-derived pancreatic cancer cells." (PMID 23094050, 2012). "Very recently, novel STAT3 phosphorylation inhibitors were demonstrated to suppress growth in pancreatic cancer cell lines." (PMID 22615549, 2012). "EGCG inhibited STAT3 transcriptional activity in a dose-dependent manner in pancreatic cancer AsPC-1 and PANC-1 cells." (PMID 22348037, 2012). "We demonstrated that XZH-5 inhibited STAT3 phosphorylation (Tyr705) and STAT3 activities, down-regulated STAT3 downstream targets, inhibited colony formation, cell migration, and induced apoptosis in human breast and pancreatic cancer cells." (PMID 23056374, 2012). "Constitutive activation of Signal Transducers and Activators of Transcription 3 (STAT3) signaling is frequently detected in breast and pancreatic cancer." (PMID 23056374, 2012).